MUC16 (mucin 16, cell surface associated)
Diseases named in the same sentence as MUC16 in open-access papers (continued):
Sharing a sentence is not in itself a finding about the gene and the disease.
tumor (continued). "The expression of MUC16 is associated with changes in signal transduction and gene expression that can lead to tumor invasion through the AKT/ERK pathway, similar to the function of the TIMP2–MMP14 complex." (PMID 35954348, 2022). "MUC16 upregulation has been linked to tumor cell invasion, aggressiveness, and metastasis in a variety of cancer types." (PMID 36552994, 2022). "The other malignant population expressing CA125 (MUC16) is associated with a decrease in the number of tumor-infiltrating cytotoxic T lymphocytes (CTLs)." (PMID 35892844, 2022). "We found that MUC16 enhances tumor malignancy by activating the integrin-linked kinase and focal adhesion kinase (ILK/FAK)-signaling axis." (PMID 35628269, 2022). "As the second longest gene in the genome, MUC16 has a high mutation frequency, which is associated with significant tumor mutation load." (PMID 35935970, 2022). "An altered tumor microenvironment signature was also identified in GC samples with MUC16 mutations; it was characterized by significantly decreased infiltration regarding stromal cells, CD4+ T cells, and macrophages." (PMID 35211490, 2022). "Although we discovered a high frequency of MUC16 mutation in G34-DHGs, only one case in the MUC16 mutation group showed abnormal high immune infiltration with abundant tumor-infiltrating lymphocytes and this patient survived up to 75 months." (PMID 35109850, 2022). "Tumors with MUC16 mutations exhibited a higher tumor mutational burden and more abundant neoantigen compared with that of MUC16 wild-type tumors, indicating increased tumor immunogenicity." (PMID 35109850, 2022). "In low-WM score group, the top genes with the highest mutation frequency were KRAS (26%), TTN (26%), and MUC16 (24%), showing that the high-WM score group had more tumor mutation burden than the low-WM score group." (PMID 35154267, 2022). "An altered tumor microenvironment signature was also identified in GC samples with MUC16 mutations, as characterized by decreased infiltration of stromal cells, CD4+ T cells, and macrophages." (PMID 35211490, 2022). "The present results demonstrated that the presence of MMs in MUC16 was associated with higher tumor markers and vascular invasion." (PMID 36199046, 2022). "In a previous publication, we identified OvCa-associated HLA class I- and HLA class II-presented tumor antigens with MUC16 and MSLN representing the two main tumor antigens for HLA class I and HLA class II, respectively." (PMID 35565389, 2022). "While oncoplots of each P0 tumor and the respective passaged PDXs depict deleterious missense mutations in many genes, it is noteworthy that deleterious missense mutations in MUC16 are present among all of the P0 tumors and their respective passaged PDXs." (PMID 36612255, 2022). "Since the tumor model we used for this experiment has sustained levels of MUC16 expression, immune escape by antigen loss or downregulation is an unlikely mechanism of disease progression." (PMID 33936101, 2021). "TTN and MUC16 were detected with high mutation frequencies in tumors expressed in the high-risk group, and they are well-known tumor-associated genes." (PMID 33619234, 2021). "In this study, we correlated the MUC16 mutational status with the following: tumor mutation burden (TML), multiple immune-related signals in microenvironment, deregulated pathways, survival outcome, and immunotherapeutic efficacy." (PMID 32491995, 2020). "For instance, patients with MUC16 mutations exhibited higher tumor mutational burden and neoantigen load, compared with patients with wild-type tumor, indicating increased tumor immunogenicity." (PMID 32845327, 2020). "The median (interquartile range) tumor variation burden was significantly higher in the group with MUC16 variant tumors than in the group with MUC16 wild-type tumors (8.5 [7.7-9.4] vs 2.8 [2.0-4.2]; P < .001)." (PMID 32530468, 2020).
tumor (continued). "MSLN and MUC16 co-expression, assessed by immunohistochemistry, was reported to be associated with increased tumor cell invasiveness and metastasis, and poor clinical outcomes of PDAC patients." (PMID 32517181, 2020). "Siglec9 promoted tumour cell adhesion process through the recognition of MUC16 glycans which contain α2,3-linked Sia, the ligand of Siglec9." (PMID 32322597, 2020). "CA125 is a large membrane glycoprotein encoded by the gene MUC16 and was identified as a tumor marker for EOC in 1983." (PMID 33036656, 2020). "In ovarian and pancreatic cancers, the role of MSLN in tumor progression/invasion has been associated to MUC16 (CA125), the only described binding partner of MSLN." (PMID 32612258, 2020). "It has been reported that tumor-associated Treg promote tumor cell escape from the immune system, MUC16/CA125 can repress antitumor immune responses through inhibiting NK cell or T cell function in many cancers." (PMID 31662990, 2019). "The IL-12-secreting MUC16 CAR was able to modify the tumor microenvironment by deleting tumor-associated macrophages and enhancing CAR T cell proliferation and cytotoxicity." (PMID 30915277, 2019). "These investigational preclinical studies justify the in-depth investigation of MUC16-targeted T lymphocytes as a potential therapeutic strategy for patients with OC using high-risk MUC16+ tumor cells." (PMID 28969098, 2017). "Interfering with cytokine actions in tumor cells then represents an avenue to develop therapeutic approaches to reduce MUC16 levels to increase cancer cell susceptibility to the host immune system and cytotoxic drugs." (PMID 26918940, 2016). "Two genes, PDE4DIP (mutated in 4 tumours) and MUC16 (mutated in 2 tumours) carried 11 somatic variations each, making them the most mutated genes in the dataset." (PMID 27829003, 2016). "Further, our results show that CRISPR/Cas9-based MUC16 knockout cells show decreased tumor-associated carbohydrate antigens (T and Tn) in PDAC cells, which suggests for the decreased lectin binding observed in this study." (PMID 27382435, 2016). "Expression of MUC16 is associated with immune protection by interfering with the formation of synapses between tumor cells and natural killer (NK) cells." (PMID 27483328, 2016). "Further, CRISPR/Cas9-mediated MUC16 knockout cells show decreased tumor-associated carbohydrate antigens (T and Tn) in PDAC cells." (PMID 27382435, 2016). "The in vivo association of cytokine expression with that of MUC16 was assessed with immunohistochemical staining of a multi-tumor human tissue microarrays." (PMID 26918940, 2016). "In contrast, the HPV-positive tumor had five mutations in four different mucin genes, including the secreted Muc6, and the transmembrane bound Muc4, Muc12 and Muc16." (PMID 23304554, 2012). "There was a progressive increase in the expression of MUC16 with loss of tumor differentiation, with 50% of the well-differentiated (6/12), 59% of the moderately differentiated (13/22) and 66% of the poorly differentiated PC tissues (16/24) being positive." (PMID 22066010, 2011). "Moreover, the co-expression of MSLN and MUC16 was associated with higher histologic grade, vascular invasion and tumor recurrence rates in pancreatic cancer and portended poorer recurrence-free survival and overall survival in affected patients." (PMID 41400642, 2025). "Moreover, elevated levels of MUC16 are associated with tumor invasiveness, lympho-vascular invasion, tumor heterogeneity and poor prognosis." (PMID 40655139, 2025).
tumor (continued). "The mechanisms by which MUC16 mutation leads to a better prognosis may vary across different tumours." (PMID 38825709, 2024). "MUC16 deletion induced an increase in the proportion of perforin+ and granzyme B+ cells in the T cells, suggesting that the presence of MUC16 is associated with the dysfunction of T cells in the tumor microenvironment of NPC." (PMID 39219440, 2024). "MUC16 mutation may be an independent influencing factor for tumors with higher tumor mutation load (TML) and longer median survival, and may be a new means to predict the sensitivity of anti-programmed death 1 (PD-1) therapy." (PMID 38758220, 2024). "MUC16 has recently been found to have a strong association with tumor mutation burden (TMB)." (PMID 38758220, 2024). "Patients with TTN, MUC16 mutations have a higher tumor mutation load and may benefit from immunotherapy." (PMID 38562942, 2024). "MUC16 mutations may be associated with a higher tumor mutation load (TML), better survival outcomes, immune response, and cell cycle pathways." (PMID 38200058, 2024). "In NIH: OVCAR3 cells, downregulation of MUC16 on the cell surface reduces DNA repair, increases DNA damage caused by genotoxic drugs, and selectively sensitizes tumor cells to genotoxic drugs by downregulating FOXO3a expression levels and reducing FOXO3a nuclear localization." (PMID 38758220, 2024). "Furthermore, a comprehensive IPM-based analysis of how MUC16 mutation affected the tumor immune microenvironment (TIME) of LUAD was performed." (PMID 37341998, 2023). "ch5E6 binds and interferes with MUC16-associated oncogenesis, suppresses the downstream signaling pFAK(Y397)/p-p70S6K(T389)/N-cadherin axis and exert antiproliferative effects in cancer cells, 3D organoids, and tumor xenografts of both PC and NSCLC." (PMID 37567918, 2023). "Moreover, MUC16 was widely reported as a frequently mutated gene in GC and was thought to be related to tumor mutation burden (TMB)." (PMID 36450891, 2023). "We found that ENST00000397910.8:c.12272T>A was the most common missense variant detected in MUC16 in the tumour and the margin samples of OPSCC patients, which suggests that it could also be a population-specific polymorphism." (PMID 37504272, 2023). "MUC16 has in combination with other serum tumor markers been shown to be associated with survival but has to our knowledge not previously been shown to be an independent factor after adjusting for all other clinically used prognostic factors in previously untreated MBC." (PMID 36945037, 2023). "MUC16 overexpression has been associated with tumor progression, metastasis, and a poor prognosis, albeit the exact mechanism is unknown." (PMID 37664708, 2023). "Furthermore, the tumor microenvironment signature was found to be different in GC samples with various MUC16 mutation statuses." (PMID 35211490, 2022). "Finally, although the mutations in TTN and MUC16 appeared to be relatively common (24% and 10%), these two genes have rarely been recognized as tumor-associated genes." (PMID 35359413, 2022). "A previously published pan-cancer analysis of 30 solid tumor types showed that patients with MUC16 mutations showed higher tumor mutation burden and neoantigen burden, indicating increased tumor immunogenicity, which can predict immune checkpoint inhibitor treatment response." (PMID 35109850, 2022). "Our findings revealed that the MUC16 mutation could suppress GC progression via regulating several tumor-related pathways in cell cycle, RNA degradation, and metabolism." (PMID 36051359, 2022). "MUC16/CA125 is associated with cancer proliferation in several tumor entities." (PMID 36230626, 2022). "In contrast, MUC16 (−) was associated with larger tumor size (p < 0.001)." (PMID 36230626, 2022).
tumor (continued). "Moreover, the mutation of MUC16 in solid tumors has been reported to be correlated with a higher tumor mutational burden." (PMID 35846431, 2022). "We also identified an altered tumor microenvironment signature in GC samples with MUC16 mutations." (PMID 35211490, 2022). "Although the differences between SMs and MMs require further investigation, this may explain the association between mutations in MUC16 and high tumor marker levels and vascular invasion." (PMID 36199046, 2022). "Similarly, mutations in MUC16, the gene that encodes the tumor antigen CA 125, have also recently been shown to correlate with tumor mutation load and improved clinical outcomes in GC patients." (PMID 31941061, 2020). "Additionally, high TML was also observed in tumor samples with MUC16 mutations of other immune activated tumor types (e.g., cancers of the lung, colorectal, kidney, bladder, and head and neck) in the TCGA cohort (Wilcoxon rank sum test, all P < 0.001)." (PMID 32491995, 2020). "On the other hand, the upregulation of MUC16 in primary tumor and ascites-derived clones could be associated with a biologically aggressive phenotype." (PMID 32293552, 2020). "Meanwhile, other studies demonstrated that MUC16 may be implicated in enhancing the activity of pro-inflammatory pathways in tumor." (PMID 32491995, 2020). "Many of the neoantigens with lasting immunogenicity in long term survivors were contained within the tumor-associated MUC16 antigen; with metastatic progression, loss of MUC16 clones was seen, indicating a role for the loss of those neoantigens in tumor progression and metastasis." (PMID 30804938, 2019). "For example, the MUC16:M9903I mutation mentioned previously shows a significant MAF increase from the primary site to the metastatic site in both tumor samples (from 6.3% in P042_PRI to 27% in P042_LIV) and in xenografts (from 10% in P042_PRI_PDX to 37% in P042_LIV_PDX)." (PMID 26555578, 2015). "The interaction of mesothelin and MUC16 may enhance the physical association of tumor cells and contribute to spheroid formation." (PMID 17067392, 2006). "Additionally, developing CARs targeting the MUC16 transmembrane domain or FRα/MUC16 tandem CARs may help overcome tumor heterogeneity and mitigate antigen loss." (PMID 40969260, 2025). "MUC16 (alternatively known as mucin 16) is a heavily glycosylated protein with important roles in cellular maintenance and epithelial protection; however, its tumor-associated expression has been correlated with tumor cell progression and migration in numerous oncological indications." (PMID 38146364, 2023). "We hypothesize that mAb5E6, owing to the unique location of epitope close to the TM domain, has the propensity to recognize most endogenous surface-tethered forms of onco-MUC16 and modulate MUC16 CT-mediated signaling associated with tumor burden and metastasis." (PMID 37567918, 2023). "Additionally, MUC16 mutations are associated with prognosis and may be related to sites that affect tumor prognosis and progression." (PMID 37812189, 2023). "In contrast, an increase in CA125 in serum was associated with an increase in malignancy and mortality, suggesting that mutations in MUC16 may affect the structural stability of MUC16, causing the tumor-derived protein to shed from the surface of hepatocarcinoma cells." (PMID 36199046, 2022). "Besides, MUC16 mutation is associated with prognosis and maybe a site affecting tumor prognosis and progression." (PMID 35646092, 2022). "Interestingly, TTN, PIK3CA, MUC4, KMT2C, and MUC16 were the top mutations in both cohorts, which were reported to regulate various tumor biological processes in CC, indicating that they are less participated in the process of immune infiltration but mainly involved in tumorigenesis and progression." (PMID 33553190, 2021).
tumor (continued). "The proteolytic processing that occurs when the MUC16 is shed from the surface of the tumor cells or subsequent digestion of the N-linked glycans by glycosidases in the peritoneal fluid may alter the soluble MUC16 and make it a less effective ligand for mesothelin." (PMID 17067392, 2006). "Single‐cell transcriptomic analyses have demonstrated that specific subpopulations, such as tumor cells expressing biomarkers like CA125 (MUC16) and tumor‐initiating cells with stem cell properties, are significantly associated with poor prognosis." (PMID 41584724, 2026). "The expression profiling of overexpressed MAMs explored the cancer‐specific overexpression of MUC3A, MUC4, MUC13, and MUC16 in tumor samples as compared to control." (PMID 41142718, 2025). "We have previously published a second generation CD28ζ co-stimulated CAR-T cell targeting the tumor retained portion of Muc16/CA-125 (4H11) and generated armored versions expressing CCR2b (4H11-CCR2) and CCR5 (4H11-CCR5)." (PMID 41424784, 2025). "Carbohydrate antigen 125 (CA125), also known as MUC16, is a high-molecular-weight transmembrane glycoprotein originally recognized as a tumor marker in ovarian and colorectal cancer." (PMID 41157213, 2025). "Given its irregular overexpression across tumours, MUC16 holds promise as a prospective target for cancer diagnosis and therapy." (PMID 40478193, 2025). "We generated human M2 macrophages from blood derived CD14 + monocytes and co-cultured them with either CD20 + Raji tumor cells or MUC16 + SKOV3 tumor cells that were both transduced with FireFly Luciferase for measurement of tumor cell viability." (PMID 40408355, 2025). "For instance, the HN1 antibody, which targets full-length MSLN, not only effectively inhibits the binding of MSLN to MUC16 but also induces cell death in MSLN-positive tumor cells through its antibody-dependent cellular cytotoxicity (ADCC) mechanism." (PMID 41400642, 2025). "Several studies have identified CA125/MUC16 as a tumor microenvironment factor, often elevated (above the normal 35 U/ml level) in the serum of up to 40% of FL and other NHL patients." (PMID 40583906, 2025). "Normally, MUC16 protects the apical surface of epithelia, but its overexpression on solid tumors promotes tumor progression, metastasis, and immune escape by directly suppressing host defense cells." (PMID 40457720, 2025). "On the other hand, “Tissue Invasion and Metastasis”, involving 18 genes such as MUC16, FGF4, and MAP3K1, remains one of the leading causes of mortality in BC patients, emphasizing the importance of these genes in the tumor’s ability to spread to other tissues." (PMID 40136626, 2025). "Preclinical studies suggest that combining a CD3-engaging TCE with a CD28 bispecific greatly enhances T-cell proliferation and tumor eradication, without systemic T-cell overactivation, as co-stimulation is restricted to MUC16-positive tumor cells." (PMID 40643516, 2025). "Cleavage of MUC16 occurs under conditions of cellular homeostasis, tumor progression, and inflammation, which facilitates the release of its N-terminal domain into circulation, making CA125 a valuable biomarker." (PMID 40305342, 2025).